TADA3 (transcriptional adaptor 3)
Description:
Functions as a component of the PCAF complex. The PCAF complex is capable of efficiently acetylating histones in a nucleosomal context. The PCAF complex could be considered as the human version of the yeast SAGA complex. Component of the ATAC complex, a complex with histone acetyltransferase activity on histones H3 and H4.
Synonyms: hADA3; ADA3; TADA3L; FLJ20221; FLJ21329; NGG1; STAF54
Tractability: PROTAC: UniProt records ubiquitination sites on it; ubiquitination databases record sites on it; its protein half-life has been measured.
Gene: Protein-coding gene on chromosome 3 (9,779,964 to 9,793,011, reverse strand). Ensembl gene ENSG00000171148.
Subcellular location: Nucleus
Subcellular location (Human Protein Atlas): Nucleoplasm
Pathways (Reactome):
Chromatin organization: HATs acetylate histones
Gene expression (Transcription): Formation of WDR5-containing histone-modifying complexes
Metabolism of proteins: Ub-specific processing proteases
Gene Ontology:
Molecular function: nuclear receptor binding; protein binding; protein domain specific binding; transcription coactivator activity
Biological process: negative regulation of transcription by RNA polymerase II; positive regulation of DNA-templated transcription; positive regulation of gene expression; regulation of cell cycle; regulation of cell division; regulation of DNA-templated transcription; regulation of transcription by RNA polymerase II; regulation of tubulin deacetylation; estrogen receptor signaling pathway; regulation of DNA repair; regulation of embryonic development; regulation of RNA splicing
Cellular component: ATAC complex; nucleoplasm; nucleus; SAGA complex; transcription factor TFTC complex; mitotic spindle
Genetic constraint (gnomAD): Loss-of-function variants: 25 observed, 43.2 expected, observed/expected ratio (o/e) 0.58, 90% interval 0.42 to 0.81. The upper end of that interval is the gene's LOEUF score, 0.81, which puts it in group 3 of 6, group 1 being the genes least tolerant of losing a copy. Missense variants: 436 observed, 582.21 expected, observed/expected ratio (o/e) 0.75, 90% interval 0.69 to 0.81. Synonymous variants: 233 observed, 231.81 expected, observed/expected ratio (o/e) 1.01, 90% interval 0.9 to 1.12.
Homologues: Orthologues: chimpanzee TADA3 (100% identical), dog TADA3 (100% identical), macaque TADA3 (100% identical), guinea pig TADA3 (99% identical), pig TADA3 (99% identical), mouse Tada3 (99% identical), rabbit TADA3 (99% identical), rat Tada3 (99% identical), tropical clawed frog tada3 (88% identical), zebrafish tada3l (79% identical), Drosophila melanogaster Ada3 (32% identical).
Diseases named in the same sentence as TADA3 in open-access papers:
TADA3 is named in the same sentence as 14 diseases in open-access papers, as found by Europe PMC text mining. Sharing a sentence is not in itself a finding about the gene and the disease.
TADA3 shares sentences with these, for which no sentence is quoted: tumor (8 papers); cancer (5); breast carcinoma (4); anemia (1); asthma (1); breast tumor (1); cervical cancer (1); chronic gastritis (1); gastric cancer (1); gastric tumor (1); infection (1); invasive breast carcinoma (1); ovarian carcinoma (1); viral infections (1).